ERG (ETS transcription factor ERG)
Diseases named in the same sentence as ERG in open-access papers (continued):
Sharing a sentence is not in itself a finding about the gene and the disease.
prostate carcinoma (continued). "Most chromosomal deletions occurring in prostate cancer are linked to either positive (PTEN, 3p, 8p, 16q, 17p) or negative (6q, 5q, 13q, 18q) ERG status." (PMID 32143573, 2020). "Mechanistically, endothelial cells induce ERG expression in prostate cancer cells." (PMID 33425737, 2020). "Evidence also suggests that men with TMPRSS2:ERG positive tumors may have longer prostate cancer survival after androgen-deprivation therapy (ADT) and this is further discussed in the section of AR gene polymorphisms." (PMID 33243086, 2020). "TMPRSS2:ERG fusions occur in about 50% of prostate cancers, preferably in younger patients." (PMID 33339518, 2020). "To investigate whether we could disrupt pre-mRNA splicing of the ERG oncogene in the context of prostate cancer (PCa), we first designed SSOs targeting the 3′ (E43′) and 5′ (E45′) splice-sites of exon 4 of ERG." (PMID 32581342, 2020). "In conclusion, high SFRP4 immunostaining is associated with poor prognosis and genomic instability in ERG negative prostate cancers." (PMID 32677026, 2020). "However, the ERG gene is consequently controlled by androgen receptor signaling and expressed highly in prostate cancers harboring the TMPRSS2–ERG fusion." (PMID 32992681, 2020). "Therefore, we examined the associations between diabetes and risk of developing prostate cancer defined by clinical features (stage, grade, and lethality) and molecular (TMPRSS2: ERG, PTEN) subtype taking into account screening patterns." (PMID 32467600, 2020). "For this study, we selected TMPRSS2:ERG fusion as it represents the most common genomic alteration in prostate cancer as well as the next most prevalent genomic alterations in prostate cancer which included deletion of 3p, 5q, 6q, 8p, 10q23, 12p, 13q, 16q, 17p, and 18q." (PMID 33339518, 2020). "FGF2 boosts the expression of the ERG gene in prostate cancer cells subsequently." (PMID 33425737, 2020). "Interestingly, qPCR and western blot assay demonstrated that the expression of ERG increased in prostate cancer cells with prolonged co-culture time." (PMID 33425737, 2020). "Notably, recurrent gene fusions of the 5′ untranslated region of TMPRSS2 to the transcription factor ERG is the most frequent genomic alteration in early- and late-stage prostate cancer and results in overexpression of ERG." (PMID 32450906, 2020). "Taken together, these results revealed that FGF2 derived from HUVEC might represent the primary source of FGF2 in the co-culture system and play a key role in inducing the expression of ERG and promoting chemoresistance to docetaxel in prostate cancer cells." (PMID 33425737, 2020). "Several studies propose that TMPRSS2 is a prostate cancer marker, as fused with the ERG gene." (PMID 32970391, 2020). "About 50–70% of prostate carcinomas harbor common chromosomal rearrangements fusing one of the ETS transcription family genes (ERG, ETV1, ETV4 or FLI1) with androgen-regulated genes, most commonly TMPRSS2, leading to disruption of androgen receptor signaling via activation of EZH253." (PMID 32873863, 2020). "That elevated TFAP2D expression was significantly associated with the majority of the analyzed deletions in ERG negative cancers highlights that elevated TFAP2D levels are either a cause or a consequence of genomic instability in prostate cancer cells." (PMID 32143573, 2020). "In summary, ERG drives the prostate-cancer-specific lineage genes by regulating SEs." (PMID 33299103, 2020). "Most deletions in prostate cancer are linked to either ERG negative cancers (i.e., deletions of 5q, 6q, 13q, 18q) or ERG positive cancers (i.e., deletions of 3p, 8p, 10q (PTEN), 12q, 16q, 17q)." (PMID 32488048, 2020). "Moreover, the development of YK-4-279, a small molecule inhibitor of ETS factors, reduced invasion, motility, and metastasis of ERG positive cells in prostate cancer." (PMID 31817884, 2019).
prostate carcinoma (continued). "Moreover, we also suggest that molecular studies should be performed in patients with prostatic carcinoma to look for T/E fusion gene and its correlation with ERG protein expression." (PMID 30658688, 2019). "Therefore, we compared ERG-bound gene targets in HUVEC with those from human prostate epithelial cancer cell line (VCaP) prostate cancer cells carrying the TMPRSS-2:ERG gene fusion." (PMID 30892142, 2019). "Its expression is associated with ERG expression and TMPRSS2: ERG rearrangement in prostate cancer." (PMID 35582143, 2019). "Thus, ERG fusion proteins alter the response of prostate cancer cells to palbociclib which has been demonstrated in human cell lines and mouse xenograft models." (PMID 31007851, 2019). "According to these observations it was suggested that combinatorial targeting of NOTCH and AR signaling may have a therapeutic potential in advanced prostate cancers bearing ERG rearrangements." (PMID 31366128, 2019). "A study in 2005 demonstrated that the chromosome 21 genomic fusion event TMPRSS2-ERG, between the transmembrane protease serine 2 TMPRSS2 and the members of the ETS (erythroblast transformation-specific) transcription factor family ERG, is common in prostate cancer." (PMID 31275657, 2019). "This study aimed to validate whether 5-hydroxymethylcytosine (5hmC) level in combination with ERG expression is a predictive biomarker for biochemical failure (BF) in men undergoing radical prostatectomy (RP) for prostate cancer (PCa)." (PMID 30818754, 2019). "Indeed, TMPRSS2:ERG fusion is frequently present in prostate cancer and known to activate the Wnt pathway through overproduction of the ERG protein, fully in line with our findings." (PMID 30733525, 2019). "Notably, in all TMPRSS2::ERG fusions present in prostate cancer, we identified more than one fusion splicing isoform." (PMID 31491926, 2019). "This compound has potential for further development of ERG-targeted therapy of prostate cancer." (PMID 31366128, 2019). "According to the ensemble of these observations, it was concluded that ERG activation, induced by the TMPRSS2-ERG rearrangement, has an important role in prostate cancer progression and cooperates with PTEN haploinsufficiency to promote prostate cancer progression." (PMID 31366128, 2019). "Interestingly, the CHD1 loss/deletion was more frequent among Chinese primary prostate cancer patients than in corresponding Caucasian patients (31% vs. 16%); conversely, Chinese prostate cancers exhibited only 6% of ERG gene rearrangements." (PMID 31366128, 2019). "Moreover, 3p13 deletion defines a subgroup of ERG+ prostate cancers characterized by aggressive clinical features and tumor recurrence." (PMID 31306099, 2019). "ERF mutations cause decreased protein stability and occur in prostate cancers without ERG upregulation." (PMID 31366128, 2019). "Next, we performed IHC to characterize ERG expression in prostate cancer tissues." (PMID 30291252, 2018). "We used MELODI, therefore, to assess the literature on ERG and prostate cancer." (PMID 29342271, 2018). "This ERRα-ERG positive feedback loop between ERRα and ERG may help to explain their concomitant increased expression patterns in advanced prostate cancer." (PMID 30042415, 2018). "ERG serves as an actuation factor in the development of prostate cancer." (PMID 30237984, 2018). "Many follow-up studies have been conducted to understand how ERG promotes prostate cancer." (PMID 30291252, 2018). "Based on these findings, we hypothesize that the ERG expressed by T:E fusion gene could target to the ERRα gene in prostate cancer cells." (PMID 30042415, 2018). "Together with the direct ERRα targeting to the T:E fusion gene, our findings indicate that ERRα and ERG can form a reciprocal regulatory loop in their transactivations in prostate cancer cells and both cooperate with each other to advance the prostate cancer progression." (PMID 30042415, 2018).
prostate carcinoma (continued). "ERG is an important factor that contributes to prostate cancer progression." (PMID 30291252, 2018). "The results of our study identify BCAR1 as a prognostic biomarker with potential clinical value for risk stratification of ERG-negative prostate cancer." (PMID 29304771, 2018). "In prostate cancer, the 5′-untranslated region of the TMPRSS2 gene is often translocated to the v-ets avian erythroblastosis virus E26 oncogene homolog (ERG) and ETS variant 1 (ETV1) gene, a member of the ETS gene family that is involved in a wide variety of functions, including cell proliferation." (PMID 29707137, 2018). "This metastasis-promoting mechanism may be particularly important in prostate cancer overexpressing ERG due to gene fusion events involving ERG." (PMID 30291252, 2018). "Since ERG-rearrangement are less frequent in prostate cancers of African descents, we explored whether candidate gene defects found in the ERG-negative group are present or absent in prostate cancers of AA men." (PMID 30150711, 2018). "ERG is reported to be a driver of carcinogenesis in prostate cancer." (PMID 29697361, 2018). "Accumulating data on ERG negative prostate cancer will help to discover more disease progression associated and actionable driver genes." (PMID 30150711, 2018). "Our data suggest that together with the demonstrated oncogenic roles performed by ERRα and ERG, combined evaluation of co-expressions of ERRα and ERG may provide a better prognosis for prostate cancer or predictor of sensitivity to hormone therapy." (PMID 30042415, 2018). "While TMPRSS2-ERG status still was a major discriminating feature in the integrative clustering analyses, we identified a third thus far unknown prostate cancer subtype that contained both high and low ERG expression samples." (PMID 30464211, 2018). "Clinical and preclinical studies demonstrate that T:E fusion is detected in premalignant prostatic intraepithial neoplasia (PIN) lesions and targeted in vivo expression of ERG can induce PIN lesions in transgenic mouse prostate, suggesting that ERG plays a casual role in prostate cancer initiation." (PMID 30042415, 2018). "Aberrant levels of FOXP2 factor were found in different types of prostate cancers, strong levels being linked to poor prognosis in ERG fusion-negative prostate cancers." (PMID 29725501, 2018). "Intriguingly, our studies showed that ERRα and ERG could positively regulate each other at their gene promoters and appear to constitute a reciprocal loop in prostate cancer cells." (PMID 30042415, 2018). "The ERG level in prostate cancer increased with the Gleason score." (PMID 30291252, 2018). "Given that ERG is able to antagonize AR function in prostate cancer cells, it will be interesting to explore whether ERG regulation of YAP1 also relies on antagonizing the repressing actions of the AR/DNMT3a complex." (PMID 29383141, 2017). "Additionally miR-200c was shown to be repressed by TMPRSS2-ERG fusion proteins and downregulated in ERG-positive prostate cancer." (PMID 28783103, 2017). "ERG activation is the most frequent molecular alteration in prostate cancer." (PMID 28515422, 2017). "For instance, the proto-oncogene ERG is a target of miRNA-145 in prostate cancer." (PMID 28177900, 2017). "The results of this study show that a high level of γ-glutamyl-hydrolase is associated with early PSA recurrence in ERG-negative prostate cancers." (PMID 28146062, 2017). "Given that the patient data demonstrate heterogeneity of ERG expression in TMPRSS2:ERG positive prostate cancer, we cannot completely exclude the possibility that VDR-mediated induction of ERG will cause an increase in ERG activity in cells with low basal levels of TMPRSS2:ERG expression." (PMID 28591703, 2017).
prostate carcinoma (continued). "Moreover, recent publication shows how NOTCH pathway inhibition antagonizes the growth and invasion of TMPERSS2-ERG positive prostate cancer cells (ERG overexpressing prostate tumor) suggesting an important role of the cascade in tumor growth." (PMID 29259971, 2017). "In an analysis of 333 individual prostate cancer exomes, TCGA identified seven subtypes defined either by gene fusions involving the ETS family (59% of cases), specifically ERG, ETV1, ETV4, or FLI1, or recurrent mutations (15% of cases) in SPOP, FOXA1, or IDH1." (PMID 28423598, 2017). "Though PTEN loss is associated with an increased risk of biochemical recurrence regardless of ERG status, when prostate cancer specific death is used as an outcome, ERG-negative tumors with PTEN loss appear to have the highest risk." (PMID 28186998, 2017). "ERG is a proto-oncogene that plays a key role in the pathology of prostate cancer." (PMID 28382513, 2017). "The question of whether VDR agonist would be beneficial or harmful in TMPRSS2:ERG positive prostate cancer has been an important question since we observed that VDR induces its expression." (PMID 28591703, 2017). "ERG labeled, as expected, only 50% of prostate cancer metastases." (PMID 28555048, 2017). "TMPRSS2:ERG (T/E) gene fusions are present in approximately 50% of all prostate cancer (PCa) cases." (PMID 28445989, 2017). "Furthermore, in prostate cancer, βIII-tubulin expression is associated with both TMPRSS2:ERG rearrangement, ERG expression and PTEN deletions, three key oncogenetic features in metastatic prostate cancer." (PMID 28677634, 2017). "FISH has also been used to analyze ERG rearrangement in prostate cancer CTCs." (PMID 26980749, 2016). "The second possibility is that ERG might also regulate the expression of protein-coding genes in prostate cancer, in addition to miR-200b subfamily." (PMID 27191272, 2016). "Moreover, ERG controls a gene regulatory network related to the development of prostate cancer, and its progression to metastatic disease." (PMID 27626314, 2016). "Such controversy on the prognostic value of ERG in prostate cancer might be due to the following reasons." (PMID 27191272, 2016). "The data reveal a very high rate of ERG heterogeneity in prostate cancer patients." (PMID 27530104, 2016). "TMPRSS2:ERG fusions are frequent in prostate cancer, and occur predominantly in young patients." (PMID 27530104, 2016). "Our previous discovery of USP9X as an ERG-stabilizing deubiquitinase suggests that reduction of ERG protein levels by TRIM25-mediated proteasomal degradation is prevented by expression of USP9X in fusion-positive prostate cancer cells." (PMID 27626314, 2016). "To thoroughly evaluate the heterogeneity for MAP3K7 deletions and TMPRSS2:ERG fusion status and their interrelationship in prostate cancer, we took advantage of a newly developed heterogeneity tissue microarray (TMA) containing samples from 10 different tumor blocks of 189 large prostate cancers." (PMID 26684029, 2016). "Importantly, prostate cancer-associated SPOP mutants fail to induce ERG degradation, whereas the majority of TMPRSS2-ERG fusions encoding N-terminal truncated ERG proteins are resistant to SPOP-mediated degradation." (PMID 27200299, 2016). "Based on the high frequency of TMPRSS2:ERG fusions and the potentially high impact on prostate cells by rendering ERG dependent genes androgen regulated, attempts were made to molecularly classify prostate cancer as “fusion-type” and “non fusion-type”." (PMID 27530104, 2016). "ERG fusion is an early event in prostate cancer that triggers paramount changes of the cancer cell micro-environment, some of which may impact the likelihood for development of certain deletions." (PMID 27861151, 2016). "The TMPRSS2:ERG fusion represents the most common genomic rearrangement in prostate cancer." (PMID 27530104, 2016). "The role of ERG-fusion proteins in prostate cancer has been reviewed in detail elsewhere." (PMID 27208692, 2016).
prostate carcinoma (continued). "In support of this speculation, previous studies report that TMPRSS2/ERG fusion is indeed a predictor of favorable outcome for prostate cancer patients." (PMID 27191272, 2016). "Instead, the downstream target genes regulated by ERG could determine prostate cancer initiation and progression." (PMID 27191272, 2016). "This suggests that the likelihood of a TMPRSS2:ERG fusion event occurring may increase over time (i.e. with age), consistent with previous reports that prostate cancer incidence also increases with age." (PMID 27144529, 2016). "By taking advantage of published ERG chromatin immunoprecipitation (ChIP-Seq) data sets, we investigated if ERG directly binds to the regulatory regions near the miR-200b/a/429 cluster and miR-205 gene in prostate cancer cells." (PMID 27191272, 2016). "To determine whether urinary EVs could be used to examine other genes associated with prostate cancer we investigated the differential expression of androgen receptor (AR), BIRC5, ERG, PCA3, TMPRSS2:ERG and TMPRSS2 in Bx Pos versus Bx Neg patients." (PMID 27144529, 2016). "This region is deleted upon fusion of TMPRS22 and ERG, which is commonly found in prostate cancer." (PMID 27366948, 2016). "Several studies have examined correlation between ERG and micro-RNAs (miRNAs) in prostate cancer." (PMID 27208692, 2016). "Two recent studies have suggested that dysregulation of the SPOP ubiquitin ligase complex in ERG-overexpressing prostate cancer cells reduces ERG ubiquitination, and that stabilized ERG was responsible for the enhanced migration and invasion activities of cells carrying SPOP mutations." (PMID 27208692, 2016). "About half of all prostate cancers harbor the TMPRSS2:ERG (T2E) gene fusion." (PMID 26692910, 2015). "In addition, depletion of HES5 in 5-aza-2′-deoxycytidine-treated prostate cancer cells (both ERG-positive and ERG-negative) will allow an assessment of de-repression of the endogenous HES5 locus on gene expression and cellular phenotypes." (PMID 25560400, 2015). "In line with our data, a link between Fzd4 and ERG has been previously observed in prostate cancer." (PMID 25584796, 2015). "However, in 50% of prostate cancers, a chromosomal rearrangement of the ERG gene results in high ERG expression." (PMID 25885538, 2015). "Chromosomal deletions analyzed in large prostate cancer cohorts have so far shown striking associations with either ERG-positive or ERG-negative cancers." (PMID 26293672, 2015). "However, patients with ERG-positive high-grade prostatic intraepithelial neoplasia (HGPIN) are much more likely to progress to prostate cancer." (PMID 26310325, 2015). "In addition to the timing of expression changes in response to androgen stimulation, these data support an AR–ERG–HES1–HES6 transcriptional network in ERG-fusion positive prostate cancer cells." (PMID 25560400, 2015). "Finally, we show that overexpression of these GRPR targets is restricted to prostate carcinomas harboring ERG and/or ETV1 rearrangements, establishing their potential as therapeutic targets for these particular molecular subsets of the disease." (PMID 26097883, 2015). "Based on this, we hypothesized that ERG protein quantification methods can be of use in the diagnosis of prostate cancer." (PMID 25889691, 2015). "ERG may regulate these changes by altering expression of the histone deacetylase, HDAC1, as this is one of the most up-regulated genes in ERG-positive prostate cancer." (PMID 26310325, 2015). "Majority of prostate cancer (PCa) patients carry TMPRSS2/ERG (T/E) fusion genes and there has been tremendous interest in understanding how the T/E fusion may promote progression of PCa." (PMID 25749044, 2015).